NLRP3 (NLR family pyrin domain containing 3)
Diseases named in the same sentence as NLRP3 in open-access papers (continued):
Sharing a sentence is not in itself a finding about the gene and the disease.
Granuloma (11 papers, 2010 to 2026). A compact, organized collection of mature mononuclear phagocytes, which may be but is not necessarily accompanied by accessory features such as necrosis. "The study also found that NLRP3-deficient mice infected with S. japonicum, developed hepatosplenomegaly, liver dysfunction, hepatic granulomas, and fibrosis, and showed reduced NLRP3-dependent liver pyroptosis." (PMID 38623843, 2024). "Deficiency or inhibition of NLRP3 inflammasome can improve HF, hepatic inadequacy, liver inflammation, granuloma, and hepatosplenomegaly caused by schistosomiasis." (PMID 36389791, 2022). "Then, the soluble antigens (SEA) released by the eggs can cause granuloma inflammation, inducing the immune system to shift from Th1 to Th2 response and continuously stimulating HSCs to produce NLRP3 inflammatory body activation of intracellular caspase-1 and TGF-β expression." (PMID 41451374, 2025). "Th17.1 cells and M2 macrophages appear central in granuloma formation and fibrotic progression, while activation of the NLRP3 inflammasome represents a promising therapeutic target." (PMID 41884121, 2026). "Galectin-3 is a multifunctional glycoprotein that promotes infiltration by mononuclear cells by enhancing the production of NLRP3 inflammasome and IL-1β, which promotes granuloma and HF." (PMID 36389791, 2022). "On the contrary, the livers of Nlrp3−/− mice displayed much smaller granulomas, evidenced by significantly lower histopathological scores." (PMID 34690967, 2021). "Histological studies of liver sections from WT, Casp-1-/- and Nlrp3-/- mice at 7 dpi showed a great number of granulomas." (PMID 34912336, 2021). "By day 14, granulomas were considerably enlarged and almost replaced the liver parenchyma in Casp-1-/- and Nlrp3-/- mice when compared to those at 7 dpi, but liver sections from WT mice exhibited a smaller number of granulomas." (PMID 34912336, 2021). "In a mouse granuloma model induced by Trehalose 6.6′-dimycolate from Mycobacterium tuberculosis, granuloma formation was decreased in Nlrp3-/- mice and increased in miR-223-/- (micro-RNA downregulating NLRP3) mice compared to wild-type mice." (PMID 32751786, 2020). "Strikingly, the Pycard−/− animals formed significantly fewer granulomas per lung compared to wild type, Nlrp3−/−, and Casp-1−/− lungs." (PMID 20808838, 2010). "Importantly, NLRP3 activation has been detected in myocardial granulomas, suggesting a key role in pathogenesis and supporting IL-1 blockade as a potential targeted therapy for inflammation-driven myocardial damage." (PMID 40940808, 2025). "MWCNT entering the airways of mice have been shown to elicit several pro-inflammatory events that originate from their activation of the NLRP3 inflammasome and are associated with the induction of IL-6, TNF-α, and IL-1β, formation of granulomas and development of airway fibrosis." (PMID 29922162, 2018). "To determine whether progressive and nonprogressive Mtb infections differently regulate the NLRP3 inflammasome activation, we interrogated the corresponding gene expression profile of human lung NG and FN granulomas, and rabbit lungs infected with HN878 or CDC1551." (PMID 41287823, 2025).
hematoma (11 papers, 2021 to 2026). A hematoma is a collection of blood from a vascular structure into an extravascular space. "In individuals with ICH, selective inhibitors of the NLRP3 inflammasome reduce the polarization of M1 microglia around the hematoma, increase the number of M2 cells, and reduce neuroinflammation after ICH." (PMID 36131917, 2022). "Recent studies have shown that NLRP3 signaling pathway expression is gradually up-regulated in tissues around hematoma 1–5 days after ICH." (PMID 34526897, 2021). "In a collagenase-induced ICH mouse model, verapamil administration has demonstrated efficacy in reducing TXNIP and NLRP3 expression around the hematoma region, inhibiting NF-κB activation, facilitating hematoma clearance, and improving both neuroinflammation and blood-brain barrier dysfunction." (PMID 40083546, 2025). "Furthermore, the pharmacological inhibition of NLRP3 using MCC950 also led to a reduction in hematoma size, edema, and motor impairment secondary to ICH." (PMID 40245261, 2025). "Following the initial mechanical injury caused by hematoma expansion, a secondary injury occurs, characterized by the production of reactive oxygen species (ROS) generated by NOX‐2 and neuroinflammation, which is exacerbated by the upregulation of the NLRP3 inflammasome." (PMID 40245261, 2025). "Effects of NR on (a) NLRP3, (b) ASC, and (c) Caspase-1 protein levels in the peri-hematoma tissue 24 h following ICH." (PMID 38981960, 2025). "When the NLRP3 gene is disrupted or the NLRP3 inflammasome is suppressed, the levels of inflammatory factors in the hematoma region of the ICH decrease, leading to a reduction in hematoma size." (PMID 38449739, 2024). "To further explore the activation of the NLRP3/ASC/ caspase-1 pathway in brain tissues after ICH, we detected the protein samples from brain tissues around the hematoma by western blotting analysis." (PMID 38645501, 2024). "During the initial compression by hematoma, mechanical strain-induced P2X7 receptors can activate NLRP3 inflammasomes and caspase-1." (PMID 35370546, 2022). "For hemorrhagic stroke, NLRP3 upregulation, caspase-1 activation, and IL-1β release occur as early as 3 h post-ICH and intensify gradually in the area around the hematoma from 1 to 5 days." (PMID 35370546, 2022). "The survival rate, hematoma volume, neurofunctional outcomes, blood-brain barrier (BBB) permeability, brain edema, spatial neuronal death, NLRP3 inflammasome, inflammatory response, mitochondrial function, and mitophagy level were evaluated after ICH." (PMID 33628368, 2021). "NLRP3, ASC, and Caspase-1 levels in the peri-hematoma tissues were measured to assess whether NR plays a protective role by inhibiting inflammasome activation." (PMID 38981960, 2025). "Notably, when the NLRP3 gene is knocked out in ICH rats, the levels of IL-1β and neutrophils surrounding the hematoma decrease, leading to a reduction in brain edema severity." (PMID 38449739, 2024).
hemorrhage (11 papers, 2017 to 2023). Loss of blood from the vascular compartment to the exterior or into nonvascular body space as a result of rupture or severance of the blood vessels. "Third, how the neuron autophagy affects neuronal function after hemorrhage and the related mechanism associated with NLRP3 should be more deeply evaluated." (PMID 35620574, 2022). "In addition, because gene deficiencies in Nlrp3 inflammasome components display protective effects on the hemorrhage fever mouse model, we further investigated whether Nlrp3 inflammasome contributes to EIII-induced platelet defects." (PMID 33995345, 2021). "This study demonstrates that NKCC1 phosphorylation in the choroid plexus epithelium promotes NLRP3 inflammasome-mediated CSF hypersecretion and that NLRP3 plays an important role in the pathogenesis of hydrocephalus after hemorrhage." (PMID 35729645, 2022). "The CSF detection results proved that Na+ and K+ increased after hemorrhage, and inhibiting NLRP3 via MCC950 decreased Na+ and K+ concentrations in CSF." (PMID 35729645, 2022). "These protective mechanisms exist due to the suppression of inflammatory responses by lowering hemorrhage volumes and reducing NLRP3 inflammasome expression to recover cognitive functions." (PMID 32899709, 2020). "Blocking NLRP3 activity improved the function of the barrier following hemorrhage." (PMID 36869068, 2023). "Taken together, our results showed that Nlrp3−/− could enhance the outcome of hydrocephalus after hemorrhage." (PMID 36869068, 2023). "Therefore, we aim at neurons to explore how the NLRP3 activation in microglia/macrophages influences cognitive and motor function after hemorrhage." (PMID 35620574, 2022). "Therefore, inhibition NLRP3 activation may be a potential therapeutic strategy which could reduce subependymal edema to improve cognitive function in the management of hydrocephalus patients after hemorrhage." (PMID 35620574, 2022). "The Nlrp3 inflammasome, IL-1β, and TNF-α contributed to inflammation, coagulation defects, and hemorrhage." (PMID 33717109, 2021). "Although the NLRP3 inflammasome, as a key component of the innate immune system, promotes neuroinflammation, its role in the pathogenesis of hydrocephalus after hemorrhage has not been investigated." (PMID 35729645, 2022).
hemorrhagic stroke (11 papers, 2016 to 2024). A stroke caused by a bleed on the brain. "Impaired mitochondria can activate NLRP3-mediated pyroptosis through mtROS release, which further enhances neuroinflammation and aggravates neuronal injury in hemorrhagic stroke." (PMID 38321473, 2024). "The MDA contents were significantly reduced and SOD activities were significantly increased after intra-thalamic injection of YC-1 and MCC950, implying that blocking HIF-1α and NLRP3 suppressed the oxidative stress induced by thalamic hemorrhagic stroke." (PMID 36944982, 2023). "Next, we investigated the role of HIF-1α and NLRP3 in the inflammatory cascade and oxidative stress after thalamic hemorrhagic stroke by analyzing the expression of several pro-inflammatory cytokines and two key oxidative stress markers, MDA and SOD." (PMID 36944982, 2023). "We found NLRP3 inhibition prevented both the increased IL-1β expression and the microglia morphology shift typical of hemorrhagic stroke." (PMID 34284798, 2021). "Inhibited NLRP3 proteins using special antagonist attenuate brain injury and inflammation after hemorrhagic stroke." (PMID 32908485, 2020). "NLRP3 inflammasomes were increased in the microglia of mice with hemorrhagic stroke." (PMID 38321473, 2024).
intestinal inflammation (11 papers, 2013 to 2025). "In previous studies, we also discovered that ADA and NLRP3 were elevated in liver cirrhosis and gastroenteritis, which was associated with the results of this experiment." (PMID 36157218, 2022). "The activation of PPAR-α receptors prevents NLRP3 hyper-activation, which is linked to several inflammatory syndromes, including intestinal inflammation." (PMID 36009057, 2022). "TLR higher expression, along with downstream activation of the NF-κB pathway, suggests the involvement of the NLRP3 inflammasome in the pathogenesis of NSAID-associated intestinal inflammation." (PMID 30555323, 2018). "Berberine (BBR) is traditionally used to treat diarrhea and gastroenteritis and has been reported to inhibit NLRP3 inflammasome activation." (PMID 37243097, 2023). "Berberine (BBR), a natural isoquinoline alkaloid isolated from several traditional Chinese herbal plants, is traditionally used to treat diarrhea and gastroenteritis, and it was reported to inhibit the activation of the NLRP3 inflammasome." (PMID 37243097, 2023). "Although there are many types of inflammasomes, the NLRP3 inflammasome is the most extensively studied and the most complicated caspase-1 inductor in intestinal inflammation and colonic neoplasia." (PMID 28380426, 2017). "We demonstrate that miR-369-3p may ameliorate the inflammatory state of IBD patients by modulating the NLRP3 inflammasome complex, thereby suggesting potential new therapeutic approaches in intestinal inflammation." (PMID 37681916, 2023).
Kawasaki disease (11 papers, 2019 to 2026). A rare inflammatory disease characterized by an acute febrile, systemic, self-limiting, medium-vessel vasculitis primarily affecting children. "Despite its pivotal role in inflammation, including in Kawasaki Disease, the activity of the NLRP3 pathway in MIS-C is poorly understood." (PMID 38762592, 2024). "In Kawasaki disease, NLRP3 inflammasome mediated interleukin 1 (IL-1) family cytokines are important drivers of vasculitis activation, and these cytokines are also increased in MIS-C17." (PMID 38762592, 2024). "ROS potentiated persistent activation of NLRP3 inflammasome in microglia after whole‐brain radiation; and mediated the pyroptosis of peripheral blood mononuclear cells via activating the NLRP3 inflammasome in Kawasaki disease." (PMID 40989573, 2025). "In addition, a recent report found that the Dectin-2/Syk/JNK/NF-κB pathway induces NLRP3 and pro-IL-1β expression in Kawasaki disease, which is similar to our conclusion." (PMID 34603335, 2021). "HMGB1 is reported to induce signalling via the RAGE receptor and the HMGB1/RAGE/cathepsin B signalling pathway, which activates NLRP3-dependent coronary endothelial cell pyroptosis and thus plays an important role in the endothelial damage that occurs in Kawasaki disease." (PMID 32795339, 2020).
osteosarcoma (11 papers, 2019 to 2026). A usually aggressive malignant bone-forming mesenchymal neoplasm, predominantly affecting adolescents and young adults. "The results obtained in this study observed overexpression of the NLRP3 protein in osteosarcoma tissues, which was closely associated with clinicopathological characteristics including poor response to chemotherapy and distant metastasis." (PMID 34393801, 2021). "Therefore, our study aimed to evaluate the expression of NLRP3 in osteosarcoma and its association with clinicopathological parameters of patients, and further explore the in vitro and in vivo effects of NLRP3 on the biological behaviors of osteosarcoma." (PMID 34393801, 2021). "Association between NLRP3 expression and clinicopathological characteristics in osteosarcoma." (PMID 34393801, 2021). "Therefore, NLRP3 plays a crucial pathogenic role for the tumorigenesis of osteosarcoma." (PMID 34393801, 2021). "Therefore, NLRP3‐inflammasome may be the underlying molecular mechanism of HTR2B in osteosarcoma." (PMID 40387572, 2025). "In summary, our study identifies HTR2B as a critical tumor suppressor in osteosarcoma progression, functioning through the NLRP3 inflammasome pathway." (PMID 40387572, 2025). "Recently, Santos‐Ruiz laboratory revealed synergic antitumor effects of Oridonin and doxorubicin in human osteosarcoma cells, although mechanistic evidences that link this outcome with NLRP3 inflammasome are still missing." (PMID 37891577, 2023). "We established an osteosarcoma xenograft model using nude mice to evaluate the effects of NLRP3 inhibitor and gene knockdown on tumor formation in osteosarcoma in vivo." (PMID 34393801, 2021). "Nevertheless, further investigations are required to confirm the therapeutic value of NLRP3 in osteosarcoma." (PMID 34393801, 2021). "According to the CCK-8, the osteosarcoma cell viability gradually decreased with the increase of CY-09 (NLRP3 inhibitor) concentration and the treatment time." (PMID 34393801, 2021). "Our study aimed to investigate the role of NLRP3 in the malignant biological behavior of osteosarcoma as well as its therapeutic value." (PMID 34393801, 2021). "NLRP3 inhibition influences the biological behaviors of osteosarcoma via the NLRP3/Caspaseaspase-1/GSDMD pathway." (PMID 34393801, 2021). "The difference in the NLRP3 expression between osteosarcoma and osteochondroma specimens was significant." (PMID 34393801, 2021). "Immunohistochemistry was applied to investigate the NLRP3 expression in osteosarcoma and osteochondroma specimens." (PMID 34393801, 2021). "The results showed that the NLRP3 protein was overexpressed in osteosarcoma, which was independently correlated with the poor prognosis of patients." (PMID 34393801, 2021). "Cell Counting Kit-8, colony formation, wound healing, transwell, and flow cytometry assays were used to explore the contribution of NLRP3 to the proliferation, migration, invasion, apoptosis and cell cycle distribution of osteosarcoma cells in vitro." (PMID 34393801, 2021). "Our in vivo results confirmed that the inhibition of NLRP3 suppressed the tumor formation of osteosarcoma." (PMID 34393801, 2021). "IHC was first used to investigate the expression of NLRP3 in 55 osteosarcoma and 30 osteochondroma tissues." (PMID 34393801, 2021). "The expression changes of proteins in this signaling pathway were observed in osteosarcoma cells undergoing CY-09 treatment and gene knockdown of NLRP3." (PMID 34393801, 2021). "ROC curve analysis for PFS and OS in osteosarcoma with different expression scores of NLRP3 protein." (PMID 34393801, 2021). "Western blot was performed to evaluate the expression of NLRP3 and the related proteins in osteosarcoma cell lines after the blockade of NLRP3 using CY-09 and lentivirus intervention." (PMID 34393801, 2021). "The reduced migration ability of osteosarcoma cells owing to NLRP3 knockdown was also validated via the wound healing assay." (PMID 34393801, 2021).